MDM2 (MDM2 proto-oncogene)
Diseases named in the same sentence as MDM2 in open-access papers (continued):
Sharing a sentence is not in itself a finding about the gene and the disease.
tumor (continued). "This study added a new activity to the repertoire of oncogenic functions of MDM2 and provided an example of a mechanism underlying altered mitochondrial metabolism often found in tumor progression." (PMID 33127643, 2020). "We demonstrated that MDM2 and TAB1 expression was associated with histological grading, and that MDM2/MDMX expression was associated with tumor size." (PMID 31892970, 2020). "MDM2 amplification had been reported to associate with a poor clinical outcome and significantly increased tumor growth rate with anti-PD-1/PD-L1 immunotherapies." (PMID 32457845, 2020). "Globally, most of the frequently mutated genes, such as MYC, KARS, MDM2, were also regulated by various types of epigenetic modifications, implying the interactions between genetic and epigenetic processes in tumor onset and progressions." (PMID 33363566, 2020). "MDM2, which is essential only in ESCs encodes an E3 ubiquitin ligase with proto-oncogene properties that promotes cell proliferation and tumor formation." (PMID 31889988, 2019). "Several studies showed its anti-tumor efficacy in a huge number of in vitro and in vivo pre-clinical cancer models and in patients with liposarcoma associated to MDM2 amplification." (PMID 31527430, 2019). "Given the low frequency of copy number variants (CNVs) in these tumor genomes, the height and the focal nature of the MDM2 and the 2q36.3 amplicon suggest they were highly selected during the clinical history of this refractory TGCT." (PMID 30870501, 2019). "Alterations in splice site usage or selection have been shown to affect genes implicated in cancer susceptibility (BRCA1) and in tumor development or progression (e.g., MDM2, CD44)." (PMID 31683936, 2019). "Specifically, SNP309G resides in the area of the MDM2 promoter that is bound by the estrogen receptor and the largest differences in age of tumor onset associated with the G/G genotype were seen in premenopausal women." (PMID 31152665, 2019). "Previous studies suggest that upregulation of MDM2 is associated with tumor initiation and metastasis of GCT." (PMID 29651441, 2018). "MDM2 amplifications were less frequently associated with high tumor mutation burden compared with the MDM2 wild-type population (2.9% v 6.5%; P < .001)." (PMID 30148248, 2018). "While several splice variants of MDM2 are identified in tumor- as well as normal cells, their functional effects are poorly understood." (PMID 28415963, 2017).
tumor (continued). "This mdm2 SNP309 G allele accelerates tumor formation in a gender specific and hormone dependent manner." (PMID 28615518, 2017). "MDM2-overexpressing tumor cells, in turn, were less susceptible to the anticancer activities of triptolide than control cells." (PMID 27004407, 2016). "Tumor cells with MDM2 overexpression were less susceptible to triptolide plus doxorubicin combination treatment." (PMID 27004407, 2016). "An inverse correlation between miR-122* and its target gene MDM2 was detected in vivo and intra-tumor administration of miR-122* caused necrosis of extensive tissue areas and increased apoptotic cell death." (PMID 27918441, 2016). "To study the mechanism underlying MDM2 knockdown induced tumor suppression, we examined the expressions of MDM2 and cell apoptosis markers in the excised tumors after treatment." (PMID 27259273, 2016). "MDM2-overexpressing tumor cells, in turn, were less susceptible to the anticancer and chemosensitization effects of triptolide than control cells." (PMID 27004407, 2016). "Overexpression of MDM2 by enhanced protein translation was frequently observed in solid tumours and was associated with tumour progression." (PMID 25831048, 2015).
tumor (continued). "Analysis of paired tumor - metastasis samples from individual patients indicated that MDM2 overexpression or MDMX underexpression was associated with the epithelial phenotype in 50 and 75% of CaP - LN pairs, respectively." (PMID 26416355, 2015). "We used a murine model to study the phenotype and function of T cells redirected against the murine double minute protein 2 (MDM2), a tumor-associated Ag that shows low expression in many normal tissues." (PMID 25539815, 2015). "Aberrant activation of NFAT1 signaling results in the upregulation of genes associated with tumor growth and metastasis, such as MDM2 and c-Myc." (PMID 26461225, 2015). "It was described as one of the tumor associated antigens (TAA) as MDM2 was overexpressed in several kinds of tumors." (PMID 26090506, 2015). "It was reported that the oral mucosa of individuals with the murine double minute 2 (MDM2) SNP 309 GG genotype is more susceptible to environmental carcinogen exposure and results in earlier onset of tumor formation." (PMID 23593187, 2013). "Alhopuru and coworkers also reported that a healthy reference population and tumor material from their study population had approximately the same frequencies of MDM2 polymorphism." (PMID 23356517, 2013). "In humans, the SNP 309T>G in the MDM2 gene was reported to be associated with an earlier onset of tumor formation in both hereditary and sporadic cancers." (PMID 23565197, 2013). "MDM2 polymorphism in the current UCB patients was tested in DNA from tumor tissue, and hence there was a risk of bias due to chromosomal deletions on chromosome 12 (where MDM2 is located)." (PMID 23356517, 2013).
tumor (continued). "Genetic polymorphisms in the human MDM2 gene are suggested to be a tumor susceptibility marker and a prognostic factor for cancer." (PMID 23565197, 2013). "Our case further confirms sclerosing RMS as a distinct diagnostic entity and implicates MDM2 amplification in the pathogenesis of this tumor." (PMID 23766666, 2013). "The SNP309 polymorphism (T-G) in the promoter of MDM2 gene has been reported to be associated with enhanced MDM2 expression and tumor development." (PMID 24098760, 2013). "It was reported that the oral mucosa of individuals with the murine double minute 2 (MDM2) SNP 309 GG genotype is more susceptible to environmental carcinogen exposure and results in an earlier onset of tumor formation." (PMID 23226559, 2012). "It is possible that these differences between the genotype of MDM2 SNP309 and MDM4 SNP7 are due to copy number changes of MDM2 or MDM4 in the tumor sample that result in overrepresentation of one allele in the tumor sample." (PMID 22916154, 2012). "For the discordant MDM2 SNP309 sequences, 4 were heterozygous in the germline (G/T) and homozygous in the tumor (T/T), which is the allele associated with lower expression of MDM2." (PMID 22916154, 2012).
tumor (continued). "The combined influence of genetic and environmental factors on the tumor promoting effects of estrogen implicated Mdm2 as a strong contributor to the bypass of cell cycle checkpoints." (PMID 21223569, 2011). "The T to G variant was shown to result in increased Mdm2 synthesis and was found to be correlated with the risk of cancer or an early onset of tumour formation at various organ sites." (PMID 18577987, 2008).